IGF2 (insulin like growth factor 2)
Diseases named in the same sentence as IGF2 in open-access papers (continued):
Sharing a sentence is not in itself a finding about the gene and the disease.
cancer (continued). "In addition to being involved in breast development and cancer, and in colon, ovarian, prostate and fibrous sarcomas, IGF2 has been associated with LAM, as immunohistochemical studies found that IGF2 was expressed in the cytoplasm and surface of spindle-shaped LAM lung cells." (PMID 29758070, 2018). "Similarly, addition of saturating amounts of IGF2 to the parental and IMP2 deficient cancer cells causes a substantially greater fractional increase in cell number in each of the IMP2 deficient variants than in the parental cells (except IMP2 deficient SNU-423, bottom right)." (PMID 28753127, 2017). "However, until now it was not clear whether IMP2 only acts by increasing the production of IGF2 or also contributes to cancer growth in other ways." (PMID 28753127, 2017). "Thus, IRA through dimerization with IGF-1R (IGF-1R:IR) or homo-dimerization may provide mitogenic stimuli to cancer cells via IGF-2 activation." (PMID 27765027, 2016). "Thus, the association between IGF1, IGF2, and IGFBP3 and cancer risk could be evaluated on the molecular level." (PMID 22347413, 2012). "This topic merits further investigation because preclinical studies have shown that several cancers expressing high levels of IGF-2 due to IGF-2R mutation and loss of heterozygosity (LOH) are more responsive to both anti-IGF-1R antibodies and anti-sense directed against IGF-2 or IGF-1R." (PMID 22022506, 2011). "Thus, we could suggest that both the IGF2 gene and the precursor mir-493 are essential genes (in fetal tissue development and cancer growth) which might be controlled by genetic and epigenetic mechanisms driven by natural TTSs-TFO complexes." (PMID 19958507, 2009). "The findings highlight the essential function of the IGF2/PI3K and the role of CAFs in ASCC growth, highlighting that IGF2/IGF1R inhibitors are potential treatment options for this cancer." (PMID 40740483, 2025). "IGFBP-6 inhibits proliferation in cancer cells which are IGF-2 dependent and can function independently of IGF-2 to inhibit angiogenesis, senescence, and cell migration." (PMID 39698031, 2024). "On the contrary, all the cancer cell clusters had a strong connection with many of the macrophages in general (except APOC3+ and IGF2+ TAMs) when TAMs provided receptors instead, indicating possibly less specific crosstalk in this direction." (PMID 38169544, 2024). "IGF-1 stimulates most steps of cancer progression by signaling through the IGF-1 receptor (IGF-1R), and IGF-2 promotes tumor growth through binding primarily to the insulin receptor subtype A (IR-A)." (PMID 38396692, 2024). "Insulin-like growth factor 2 (IGF2) is not only a major factor in the development of primary tumors, but also plays a crucial role in cancer spread, immune evasion, and treatment resistance." (PMID 38887298, 2024). "Previous studies have determined a direct role for the SS18-SSX fusion protein in regulating expression of several cancer-related genes, such as EGR1, FOS, IGF2, FZD10, SOX2, UNCX and CDH4." (PMID 39045458, 2024). "In terms of the crosstalk between TAMs and cancer cells, several reports indicate the capability of TAMs to secrete IGF1 and IGF2, similarly to CAFs." (PMID 38892104, 2024). "In the most aggressive cancers, IR-A is currently the most prevalent IR isoform expressed, and recent studies have indicated that DDR1 has the potential to modulate the IGF-2/IR-A loop." (PMID 37834454, 2023). "The autocrine pathway would constantly supply the PI3K/AKT signal cascade, contributing to IGF-2 overexpression through a positive feedback loop mediated by PLAG1, as demonstrated in some benign and malignant tumors." (PMID 36901760, 2023). "This is reasonable considering all genes are involved in related pathways such as Proteoglycans in cancer (ERBB2, TIMP3 and IGF2) and ECM–receptor interaction (COL6A2)." (PMID 38069080, 2023).
cancer (continued). "Of note, IGF2 is approximately five-fold more abundant than IGF1 in serum and is often more expressed than IGF1 in cancer, in both an autocrine and paracrine manner." (PMID 36672737, 2023). "Coherent with the high IGF2BP2 protein levels, IGF2 RNA, which is bound by the wt IGF2BP2 protein, is also largely overexpressed in Patient 2 cancer cells compared to other patients." (PMID 38012143, 2023). "Each of two pathway categories (proteoglycans in cancer and PI3K-Akt signaling) was enriched by two hub-DEGs (TLR2 and IGF2)." (PMID 35277538, 2022). "DORexo contained enhanced levels of IGF-2 and IGFBP2, and we are wondering if the promotive effect of BMSCs on cancer cell growth in bone marrow is through activating IGF-1R." (PMID 36568212, 2022). "By regulating the bioavailability of the type-1 IGF receptor (IGF1R) ligands, IGF-1 and IGF-2, the IGF binding proteins (IGFBP-1 to -6) play essential roles in cancer progression." (PMID 35597813, 2022). "Thus, H19 could regulate the progression of cancer by changing the expression of IGF2." (PMID 36246634, 2022). "In terms of mRNA expression, GREM1, IGF2, CTGF, and PLAU showed significant changes between cancer adjacent and cancer free polyps." (PMID 35486660, 2022). "The transfer of IGF-2 and IGFBP2 from cancer cells to BMSCs enhanced the glycolysis of BMSCs, supporting cancer cell survival in the bone marrow through the production of lactic acid." (PMID 36568212, 2022). "Therefore, sharing of circ_TMEM45A between cancer cells may contribute to IGF2 upregulation." (PMID 35055115, 2022). "Several of these specialized TME microenvironments are enriched by the pan-cancer survival network, for example HIF1A signaling (p = 4.27 × 10−6; FGF2, IGF2, MMP1, MMP14, MMP3, PIK3R3, SERPINE1, TGFB1)." (PMID 35106465, 2022). "They overexpress IGF-2 and its receptor and the IGF-1 receptor, and the overexpression is most pronounced in malignant tumours." (PMID 34170845, 2021). "The IRS2, IGF2, and ATG12 proteins were present mainly in cancer metabolic pathways, including the MAPK, FOXO, and RAS signaling pathways." (PMID 34976838, 2021). "A phase Ib/II clinical trial testing the combination of BYL719 and an anti-IGF1R antibody, AMG479, showed toxicity in cancer patients (NCT 01708161), but there are also other approaches to targeting the IGF2/IGF1R axis." (PMID 34067117, 2021). "MiR-1193 was previously shown to suppress proliferation and invasion of cancer cells through directly targeting transmembrane 9 superfamily member 3 (TM9SF3), and insulin-like growth factor 2 mRNA binding protein 2 (IGF2BP2)." (PMID 33046105, 2020). "IGF2 and IGF2R are usually referred in the studies on imprinted genes and cancers, which we have also tested in our samples." (PMID 32448196, 2020). "Experimental overexpression of miR-493-5p promoted an anti-cancer response by inhibiting HCC cell growth and invasion, in part, through the negative regulation of insulin-like growth factor 2 (IGF2) and the IGF2-derived intronic oncomir miR-483-3p." (PMID 33937011, 2020). "A literature search showed that many of these altered genes, such as IGF2, FAM83A, CEACAM5 and CEACAM6, STC1 and MSMP, play a role in PCa or other types of cancer." (PMID 31500347, 2019). "Of those, the highly conserved family of insulin-like growth factor 2 mRNA-binding proteins (IGF2BPs), which includes the paralogs IGF2BP1, IGF2BP2, and IGF2BP3, primarily play oncogenic roles in cancer." (PMID 32010687, 2019). "In osteoblastic metastases, osteoblasts produce many factors including insulin-like growth factor 1 (IGF-1), insulin-like growth factor 2 (IGF-2), TGF-β, TNF-α and IL-1β that act as chemoattractants for cancer cells." (PMID 30823602, 2019). "Both stromal and epithelial cancer cells can locally produce IGF-2 and, since IR-A is a high affinity receptor for IGF-2, the autocrine/paracrine IGF-2/IR-A loop promotes cancer cell proliferation." (PMID 30453495, 2018).
cancer (continued). "Both cancer and stromal cells produce IGF-2 and therefore IR-A, in addition to IGF-1R, mediates the mitogenic and antiapoptotic effects of IGF-2." (PMID 30453495, 2018). "FZD8, plasminogen activator, urokinase receptor, ITGA2, WNT2B, TIMP3, WNT5B, FGF5, heparanase, HBEGF and WNT3A were up-regulated in the proteoglycan pathways in cancer, whereas WNT10A, PIK3R3, IGF2 were down-regulated." (PMID 30482199, 2018). "This enabled us to examine genes on an individual basis, and many genes important in the development of CRC, and cancer in general, were upregulated in the CAP tissues relative to the CFPs, including CXCL5, GREM1, IGF2, CTGF and PLAU." (PMID 29453410, 2018). "Most human cancers over express IGF-1 receptor (IGF-1R) and IGF-2 is a known ligand for the respective receptor and can bind to IGF-2 receptor (IGF-2R), which sequesters IGF-2." (PMID 30338035, 2018). "In turn, a high level of IGF2BP2 enhances the expression of IGF2 which activates the PI3K/Akt/mTOR pathway and promotes the proliferation, migration, and epithelial-mesenchymal transition of cancer cells." (PMID 29736175, 2018). "We evaluated the role of IGF2 signaling pathway in MRT cell proliferations, and also confirmed this hormone promotes cancer cell growth through stimulation of IGF1R and INSR, which is associated with activation of PI3K/AKT and RAS/ERK pathways." (PMID 28521298, 2017). "Thus, DDR1 may work as a possible novel candidate in targeting the IGF-2/IR-A loop in cancer." (PMID 28591735, 2017). "Insulin-like growth factor 2 mRNA binding protein 3 (IGF2BP3/IMP3/KOC), initially identified as an RNA-binding protein, is highly expressed in embryonic tissues and a variety of cancers." (PMID 29212181, 2017). "We have selected five PCGIs (IGF2, SLC16A12, SOX11, P2RX7 and MYOD1) from cancer and inflammation/age related panels." (PMID 27259265, 2016). "Among the six cancer cell lines, four were heterozygous (HRT18, HT29, HCT116, and ASPC) and thus informative for a SNP (C/T) located in IGF2 exon 9 which can be used to distinguish the two parental alleles." (PMID 27275535, 2016). "In order to study the role of IGF2 in the maintenance of CSC characteristics, we isolated CSCs from six cancer cell lines and examined the allelic expression and epigenetic regulation of IGF2." (PMID 27275535, 2016). "The insulin-like growth factors (IGFs), IGF-1 and IGF-2, are ligands that bind to IGF receptor (IGF-1R,) and regulate cancer cell proliferation, survival, and metastasis." (PMID 25866791, 2015). "Still, most studies focused on autocrine effects of these two secreted proteins in cancer cells, while our data suggest a paracrine effect whereby HSC derived IGF2 and IGFBP2 influence IGF-signaling in HCC cells." (PMID 26020769, 2015). "In conclusion, our data identify anti-IGF-1R monoclonal antibody-induced cancer–stromal cell communication via STAT3-dependent IGF-2 production in cancer cells and a positive IGF-2/CXCL8 feedback loop through the intercellular IGF-2/IGF-2R system." (PMID 26465273, 2015). "First, we targeted the following loci given the initial observation from TCGA: five imprinted domains (PEG3, H19/IGF2, DLK1/GTL2, MEST, GNAS) and four cancer genes (APC, MLL3, MGMT, ELF3)." (PMID 26338779, 2015). "Activation of IGF1R which is essential for the initiation and progression of many cancers starts by ligand-initiated kinase activation with IGF1 or IGF2." (PMID 25344917, 2014). "IGF-1R can be founded in most solid tumors and hematological malignancies examined to date, and IGF-2 overexpression, IGFBP modulations, and IGF-2R down-regulation have also been founded in cancer cells." (PMID 25424625, 2014).
cancer (continued). "In the present work, we investigated the role of IGF2 in ACC by several original approaches including phenotypic comparison between IGF2-high and IGF2-low ACC carcinoma, transcriptomic analysis, and knock-down of IGF2 in H295R cells with siRNA." (PMID 25089899, 2014). "Deregulation of the IGF signaling pathway frequently occurs in human cancer and involves the establishment of autocrine loops comprising IGF-1 or IGF-2 and/or IGF-1R over-expression." (PMID 23525758, 2013). "Binding of ganitumab inhibited the high-affinity interaction of IGF-1 and IGF-2 required to activate IGF1R in cells engineered for IGF1R hypersensitivity and in human cancer cell lines, resulting in complete blockade of ligand-induced cellular proliferation." (PMID 23383308, 2013). "In cancer cells with high levels of IGF1R/IR HRs, IGF1 and IGF2 activate various downstream signaling pathways through heterodimeric receptors rather than through homodimeric IGF1Rs." (PMID 22438913, 2012). "In other words, overexpression of IR serves as a major mechanism of IGF1R signaling in cancer cells by enabling the formation of more heterodimers which are available for binding ligands including IGF1, IGF2, and insulin." (PMID 22438913, 2012). "At the 5′end of IGF2 there is a differentially methylated region, DMR0, which in human has variable methylation in somatic tissues and is hypomethylated in cancers." (PMID 19956766, 2009). "The IGF signalling pathway is activated in various cancers, and monoclonal antibodies targeting IGF1R have been recently developed; IGF1R is a transmembrane tyrosine kinase receptor, and both IGF1 and IGF2 are ligands for IGF1R." (PMID 19034281, 2008). "The most investigated genes were those implicated in neuroendocrine stress responses; dopamine, norepinephrine, and serotonin signalling; apoptosis; insulin secretion; neuroplasticity; reproduction; foetal growth; and cancer (e.g. MAOA, BRSK2, ADCYAP1, BDNF, DRD2, IGF2, H19)." (PMID 41070359, 2025). "IGF2 is predominantly secreted by CAFs, whereas IGF1R is predominantly expressed by cancer cells." (PMID 38887298, 2024). "Similar to IGF2 and H19, DLK1 and MEG3 also perform diverse biological functions in cancers." (PMID 38812777, 2024). "While IGF1 reduction was attributed to non-specific surgical effects, the IGF2 decrease remained significant, especially for malignant tumours and larger sizes." (PMID 38339282, 2024). "Analysis of Igf1 and Igf2 expression levels showed that epithelial plastic cancer cells did not induce the expression of these factors, suggesting a paracrine activation of IGF1R." (PMID 39075581, 2024). "Whilst insulin-like growth factor 2 (Igf2) is an experimentally validated gene across numerous developmental and cancer contexts, it remains unclear if PLAG1 regulates Igf2 expression in the embryonic cortex." (PMID 38240991, 2024). "In addition, IGF2 transcription can be differentially affected by the various WT1 isoforms, which are expressed in a tissue- and cancer-specific context." (PMID 37371750, 2023). "TUG1 is overexpressed and oncogenic in many, though not all, cancers, but its potential actions through IGF-2 upregulation have not been explored in a cancer context." (PMID 35597813, 2022). "Both, IGF2 and its receptor IGF1R constitute desirable therapeutic targets; mainly due to these evidences showing that targeting either IGF2 or its receptor IGF1R, blocks cancer progression and displays significant antitumor activity." (PMID 35095996, 2021). "Additionally, upregulated genes of potential interest included H19 and IGF2 (adjusted p = 1.31e − 83, adjusted p = 5.04e − 08), both regulated by PLAGL1 and with known functions in the tumorigenesis of different cancers." (PMID 34355256, 2021). "Additionally, upregulated genes included H19, IGF2 and DLK1, all regulated by PLAGL1 and with known functions in tumorigenesis of different cancers." (PMID 34355256, 2021).
cancer (continued). "In addition, NF-kB can induce IGF2 expression in cancer cells to activate IGF-IR, and then promote cancer stemness." (PMID 32493414, 2020). "In order to find useful and efficient cancer biomarkers for clinical applications, we generated the ROC curves for the GNAS, GRB10, SNRPN, IGF2, and IGF2R imprinted genes using the individual BAE, MAE, and TE measurements for all the different cancer types combined." (PMID 32448196, 2020). "IGF1 promotes the development and cytotoxic activity of human NK cells, therefore the reduction of this protein by the augmented expression of IGF2 by miR-483-5p, or by the direct targeting of IGF1 by miR-483-3p, provide a protection to cancer cells by suppressing NK cells activity." (PMID 29867024, 2018). "However, an in vitro study revealed that IGF2R knockdown significantly reduced IGF2-related ERK1/2 phosphorylation, suggesting that the complex of IGF2 and IGF2R participates in cancer cell proliferation." (PMID 30168002, 2018). "Although IGF2/IGF1R and IGF2/IR complexes primarily activate intracellular signal transduction for cell proliferation, some studies have reported that IGF2/IGF2R complex plays a role in cancer progression." (PMID 30168002, 2018). "MMP2, IGF2, DCN, LUM and TWIST are involved in proteoglycans in cancer pathway." (PMID 30576338, 2018). "In its turn, IGF2 is a trigger molecule of the MAPK signaling cascade, where the signaling converges on the transcription factor NFATC2 that induces transcription of the genes from a genetic network determining the cancer properties of cells." (PMID 28031533, 2017). "The autocrine IGF2, in turn, activated insulin-like growth factor 1 receptor (IGF1R), insulin receptor (INSR), followed by PI3K/AKT pathway and RAS/ERK pathway to promote cancer cell proliferation and survival." (PMID 28521298, 2017). "We found six genes, ADIPOQ, DKK1, IGF1, IGF1R, IGF2, and PLAUR were shared by all the four cancers." (PMID 28676692, 2017). "This suggests that cancer patients whose tumors have abnormally high levels of IMP2 may be especially sensitive to drugs that target and inhibit IGF2." (PMID 28753127, 2017). "There are many types of autocrine growth factors, with the major ones in cancer being vascular endothelial growth factor (VEGF), epidermal growth factor (EGF), insulin-like growth factor-2 (IGF-2), epidermal growth factor receptor (EGFR) and 5-hydroxytryptamine (5-HT; serotonin), to name a few." (PMID 28410237, 2017). "Because all of those published studies examined the status of IGF2 imprinting in whole cancer tissues or cell lines, rather than in purified CSCs, it is likely that the true incidence of IGF2 LOI, particularly in CSCs, has been greatly underestimated." (PMID 27275535, 2016). "Therefore, to analyze the relative role of IGFBPs and IGF2R in cancer, we developed a mass-action kinetics model of the IGF network that incorporated IGF1, IGF2, IGF1R, IGF2R, and IGFBPs." (PMID 26861122, 2016). "However, the dramatic increase of IGF2 and miR-483 expression in ACC (up to several hundreds of times as compared to ACA or NA) when compared to that of other cancers suggest a critical role for IGF2 locus in adrenocortical cancer development and progression." (PMID 26834703, 2015). "We therefore assessed the role of IGF-2 and IGF-2R in cancer–stroma communication." (PMID 26465273, 2015). "The IGF2 mRNA binding protein family (IGF2BPs) is comprised of three members: IGF2BP1, IGF2BP2, and IGF2BP3, which are bona fide oncofetal proteins involved in various human cancers." (PMID 26547929, 2015). "However, the potential of this transcriptional targeting approach might be even greater if the cancer-specific promoters H19, IGF2-P3, and IGF2- P4, are utilized in the same therapeutic construct because many tumors that lack H19 gene expression have been found to express IGF2." (PMID 25884481, 2015).